NLRP3 (NLR family pyrin domain containing 3)
Diseases named in the same sentence as NLRP3 in open-access papers (continued):
Sharing a sentence is not in itself a finding about the gene and the disease.
liver diseases (continued). "It has proposed that mature IL-1β secretion requires appropriate process by NLRP3 activation and caspase-1 cleavage in various liver diseases, including alcoholic steatohepatitis, viral fulminant hepatitis, non-alcoholic fatty liver disease, and heat stroke-induced liver injury." (PMID 29692782, 2018). "NOD-like receptor protein 3 (NLRP3) inflammasome, a multiprotein complex, contributes to the development of liver disorders, such as alcoholic steatohepatitis, viral fulminant hepatitis, and non-alcoholic fatty liver disease, through processing caspase-1 cleavage and IL-1β secretion." (PMID 29692782, 2018). "Moreover, pharmacological inhibition of BRISC alleviates NLRP3-driven diseases in mouse models including methionine-choline-deficient (MCD) diet-induced nonalcoholic fatty liver disease, which indicates a potential role of BRISC in liver diseases." (PMID 37968261, 2023). "Nrf2 is a master transcription factor that increases the expression of several endogenous antioxidant genes, and its pharmacological activators have demonstrated promising protective effects in liver disease, which may be attributed to its capacity to attenuate the NLRP3 inflammasome and pyroptosis." (PMID 35624734, 2022). "Hence, NLRP3 inflammasomes might be a novel target for the treatment of liver disease, especially in FLD." (PMID 36160411, 2022). "Targeting the TXNIP/NLRP3 pathway may be promising in liver diseases." (PMID 35408890, 2022). "Whether H2S can regulate ER stress and the NLRP3 inflammasome in liver disorders is worth studying." (PMID 35408890, 2022). "The miR-17, which can suppress NLRP3 inflammasome activation by targeting TXNIP expression, is abundant in AMSC-Exo cargo; this clearly indicates that AMSC-Exo-based therapy may be a promising approach for treating TXNIP/NLRP3 inflammasome-related inflammatory liver diseases." (PMID 34440528, 2021). "In addition to the classical NLRP3 inflammasome–caspase-1 cytokine activation pathway, serine proteases from immune cells are also potent cytokine activators contributing to liver disease progression." (PMID 31507607, 2019). "Based on the findings in other sterile inflammation-associated liver diseases, one might speculate that the suppressive effect is due to impaired NLRP3 inflammasome activation in the absence of P2rx7." (PMID 30213101, 2018). "Elevated expression of NLRP3 was mainly observed in MDMs in MASH patients with fibrosis, indicating a potential link between macrophages, NLRP3, and liver disease progression." (PMID 41530833, 2026). "This review aims to evaluate the published articles related to the role of NLRP3 inflammasomes in common pediatric gastrointestinal (GIT) and hepatic disorders in order to identify future perspectives regarding their possible therapeutic values." (PMID 41149694, 2025). "Immunohistochemical analysis showed that positive immunostaining of NLRP3 and its activation marker CASP1 was detectable as brown granules in the cytoplasm of hepatocytes in liver sections of all patients with HCV-related liver disease." (PMID 36376416, 2022). "Serum NLRP3 level ranged between 800 and 2,650 pg/ml in patients with HCV-related liver disease and between 365 and 840 pg/ml in healthy controls." (PMID 36376416, 2022). "Caffeine elicits protective effects against liver diseases, such as NASH; however, its mechanism of action involving the pyrin domain-containing-3 (NLRP3) inflammasome signaling pathway remains to be elucidated." (PMID 36077357, 2022). "Therefore, we suppose NLRP3 inflammasome probably is one of the most important targets of YCHD to treat liver diseases and RFAs from rhubarb are the main components of YCHD to make the vital role in inhibiting NLRP3 inflammasome and the results also confirmed our hypothesis." (PMID 35765026, 2022).
liver diseases (continued). "NLRP3—whose domains include the NOD-like receptor protein 3 (NLRP3), adaptor molecule ASC (also referred to as PYCARD) and serine protease Caspase-1—is the inflammasome most commonly activated in liver diseases." (PMID 35052789, 2022). "It is known that various types of inflammasomes, such as NLRP1, NLRP2, NLRP3, NLRP6, NLRP10, and NLRP12, have been expressed in different hepatic diseases." (PMID 31547621, 2019). "NLRP3, a key palyer in NAFLD development, has received considerable attention in liver diseases." (PMID 38566171, 2024). "Regardless of the classification of liver diseases as acute or chronic, NLRP3 is a key player in the deterioration of the pathology." (PMID 38674122, 2024). "More importantly, signaling pathways such as Nrf2, NF-κB, PI3K/Akt/mTOR, NLRP3, Wnt/β-catenin, TGF-β1/Smad3, AMPK/SREBP, PPARα/γ, MAPKs, and Caspases are identified as key targets through which API exerts its beneficial effects in various liver diseases." (PMID 39749193, 2024). "NLRP3 is one of the most widely studied NLR family members in liver disease, which was widely distributed in parenchymal and non-parenchymal hepatocytes." (PMID 36619871, 2022). "NOD-like receptor pyrin domain containing 3 (NLRP3) is a microbial and danger signal sensor that acts as a regulator of inflammation via activation of Caspase-1 (CASP1) and has been identified as a major contributor to human liver diseases." (PMID 36376416, 2022). "Various inflammasome components, such as the nucleotide-binding domain and leucine-rich repeat family pyrin domain-containing proteins (NLRP1, NLRP2, NLRP3, NLRP6, NLRP10, and NLRP12), have been identified and found to play important roles in various experimental models and human liver diseases." (PMID 35350750, 2022). "All these results demonstrated that L-NAT could attenuate HIRI by regulating TLR4/NLRP3 signal, which would provide experimental data for the application of L-NAT in the field of liver diseases." (PMID 34434653, 2021). "NLRP3 inflammasome activation may lead to GSDMD-driven pyroptosis, which plays a key role in the occurrence and development of liver diseases." (PMID 34630100, 2021). "Undoubtedly, there is no denying that NLRP3 inflammasome plays a critically function in the pathogenesis of liver diseases and further investigations aimed to delineate the effects of NLRP3 inflammasome in liver diseases are imperative." (PMID 32211410, 2020). "Interestingly, the microbiome dysbiosis in NLRP3−/− or NLRP6−/− mice can be transferred to co-housed wide type (WT) mice and is strongly correlated with the severity of hepatic disorders." (PMID 30319645, 2018). "Upon binding to Clec7a on Kupffer cells, β-glucans activated caspase-1 via NLR Family Pyrin Domain Containing 3 (NLRP3) that leads to increased inflammatory Interleukin (IL)-1b expression and secretion, which subsequently contributed to hepatocyte damage and ethanol-induced liver disease." (PMID 39116092, 2024). "The effect of liver disease on gene expression was confirmed in multivariable models after adjustment for potential confounders (age, sex, BMI): all the inflammasome components (P2X7R, P2X4R, NLRP3, CASP1, AIM2, IL-2) were significantly related to the liver disease (0.0007 < p <0.037)." (PMID 35806450, 2022). "Thus, our findings suggest an effective strategy to prevent and/or treat liver inflammatory diseases by modulating the AMPK/SIRT1 pathway and targeting the XBP1/NLRP3 activity in macrophages using genetically modified MSC approaches or pharmacological interventions." (PMID 35842731, 2022). "Although numerous researches have reported the protective effects of OEA on various liver diseases associated with NLRP3 inflammasome activation, whether OEA could regulate the activation of NLRP3 inflammasome has not been investigated until our present study." (PMID 33536915, 2020).
liver diseases (continued). "In addition, NLRP3 inflammasome stimulates lipid droplet formation in hepatocytes, which promotes the morphogenesis and replication of HCV, thus contributing to the pathogenesis of liver diseases." (PMID 30319645, 2018). "In this way, blocking ER-dependent NLRP3 inflammasome and cell death pathways, with TUDCA alone, or combined with other hepatoprotective and anti-inflammatory interventions, may represent a valid therapeutic strategy for the treatment of liver disorders." (PMID 26355342, 2015). "However, the role of NLRP3 in HCV-related liver disease has not been fully elucidated." (PMID 36376416, 2022). "By specifically and precisely targeting key molecules in the pyroptosis pathway, such as NLRP3 and GSDMD, pathological processes of liver diseases can be alleviated without compromising the body’s immune defense mechanisms." (PMID 39917567, 2025). "Expression analysis for various inflammasomes in animal model suggested that NLRP1, NLRP3, and AIM2 were highly expressed in Kupffer cells and liver sinusoidal endothelial cells, while virtually absent in primary cultured hepatocytes in inflammatory and hepatic disease conditions." (PMID 31551961, 2019).
heart failure (112 papers, 2014 to 2025). Inability of the heart to pump blood at an adequate rate to meet tissue metabolic requirements. "The atheroprotective effect of NLRP3 inflammasome inhibitors, as well as their protection against the development of heart failure in TET2-deficient mice, supports these findings." (PMID 35657494, 2022). "Nucleotide‐binding oligomerization domain‐like receptor family pyrin domain containing 3 (NLRP3) inflammasomes are the most important factors in ventricular arrhythmia associated with heart failure (VA‐HF)." (PMID 33270361, 2021). "The findings of previous work have also suggested that selective NLRP3 inflammasome inhibition has a cardioprotective effect, reducing the risk of heart failure or other cardiovascular diseases." (PMID 34567409, 2021). "NLRP3 activation has been implicated in myocardial injury, adverse remodeling, and heart failure." (PMID 40940808, 2025). "For instance, Ca2+ flux-triggered NLRP3 inflammasome activation has been linked to postoperative atrial fibrillation, and inflammation and NLRP3 inflammasome activation driven by Ca2+ signaling have been implicated in heart failure." (PMID 38378646, 2024). "In heart failure, pirfenidone may reduce the expression of col-1 induced by TGFβ, decrease vascular permeability, and inhibit inflammation and fibrosis caused by NLRP3, thereby alleviating the development of pressure overload-induced chronic cardiac fibrosis." (PMID 38020087, 2023). "Individuals with TET2-mediated clonal hematopoiesis may have greater risk of developing heart failure and respond better to IL-1β–NLRP3 inflammasome inhibition." (PMID 32377298, 2020). "Chronic low‐grade inflammation is common in heart failure due to sustained activation of the nod‐like receptor pyrin 3 (NLRP3) inflammasome, which mediates the progression of heart failure and cardiovascular complications in the elderly." (PMID 39828641, 2025). "NLRP3 activation induced via calcium-/calmodulin-dependent protein kinase IIδ consequent to pressure overload also worsens myocardial fibrosis and heart failure." (PMID 40564905, 2025). "In murine models of pressure overload, ischemia–reperfusion injury, and heart failure, NLRP3 upregulation in the ventricular myocardium correlates with increased arrhythmic burden." (PMID 40649732, 2025). "= heart failure hospitalization, NLRP3 = nucleotide-binding domain, leucine-rich repeat, and pyrin domain-containing protein 3, ROS = reactive oxygen species, TGF-β = transforming growth factor beta, SGLT-2 = sodium-glucose cotransporter-2." (PMID 41393541, 2025). "The inflammatory mechanisms that induce instability in atherosclerotic plaques—especially NLRP3 activation, IL-1β signaling, and endothelial dysfunction—are also central to myocardial remodeling and heart failure." (PMID 40564905, 2025). "TNF-α, an inflammatory mediator, promotes cardiac fibrosis by activating the NLRP3 inflammasome, providing a potential new target for heart failure." (PMID 40552149, 2025). "In another set of mouse experiments, OLT1177, an inhibitor of the NLRP3 inflammasome, partially restored cardiac function that was compromised in heart failure." (PMID 38317229, 2024). "In heart failure, activation of the NLRP3 inflammatory mediates the release of pro-inflammatory mediators such as IL-1β and IL-18, considered significant contributors to myocardial fibrosis and cardiac dysfunction in heart failure." (PMID 39022620, 2024). "MCC950 lowered doxorubicin-induced myocardial injury by repressing NLRP3-mediated pyroptosis in in-vivo and in-vitro models as well as alleviated heart failure-induced ventricular arrhythmia." (PMID 38421496, 2024). "Collectively, NLRP3 deletion abrogated TXNIP overexpression‐induced exacerbation of heart failure in obese hearts." (PMID 39604027, 2024). "In a mouse model with Tet2 mutation, the NLRP3 inflammasome inhibitor MCC950 was administered, revealing that MCC950 prevented heart failure development." (PMID 38317229, 2024).
heart failure (continued). "In this study, we investigated the effects of CRID3, an inhibitor of the NLRP3 inflammasome, on heart failure and myocardial hypertrophy." (PMID 39553724, 2024). "NLRP3 activation in acute MI can promote adverse cardiac remodeling, systolic dysfunction, and heart failure." (PMID 38058609, 2023). "Given the role of inflammasomes in heart failure, consecutive activation of NLRP3 cannot induce an inflammatory response in the heart." (PMID 38270118, 2023). "Inflammasome NLRP-3, is a key trigger of heart failure, arrhythmias, myocarditis and cancer progression." (PMID 37684243, 2023). "And sulfur dioxide can downregulate NLRP3 expression in septic rats through the TLR4/NLRP3 signaling pathway, which in turn interferes with its downstream inflammatory cytokines and attenuates cardiac insufficiency." (PMID 37904696, 2023). "DNMT3A mutated monocytes from patients with heart failure have been shown to express higher mRNA levels of IL-1β, IL-6 and IL-8, macrophage inflammatory chemokines CCL3 and CCL4 and the inflammasome NLRP3." (PMID 36835370, 2023). "In mouse models of heart failure with hematopoietic or myeloid TET2 deficiency, IL-1β/NLRP3 inflammasome inhibitor ameliorated heart failure." (PMID 37928907, 2023). "One of the underlying intracellular mediators of inflammation that is activated in heart failure is the NLR family pyrin domain containing 3 (NLRP3) inflammasome." (PMID 37626809, 2023). "In the present study, we investigate the regulative relation of ATP6AP2, autophagic flux, and NLRP3 inflammasome activation in the progression of cardiac hypertrophy and heart failure." (PMID 35379787, 2022). "(iii) NLRP3 inflammasome significantly increases in TAC-induced heart failure after ATP6AP2 knockdown." (PMID 35379787, 2022). "It has been established that IL-1 and NLRP-3 inflammasomes are key drivers of anticancer drug-mediated cardiac dysfunctions, including heart failure, a decrease in the left ventricular ejection fraction, EF and cardiac fibrosis." (PMID 36547420, 2022). "Emerging evidence has indicated that full activation of the NLRP3 inflammasome and secretion of IL-1β and IL-18 participated in atherosclerosis, diabetes, heart failure." (PMID 35379787, 2022). "If not effectively compensated, it compromises autophagic flux, leads to dysfunctional mitochondria accumulation, further produces ROS to activate NLRP3, eventually accelerates heart failure." (PMID 35379787, 2022). "Overall, these changes indicated that during decompensated heart failure, NLRP3 activated, accompanied by blockage of autophagic flux." (PMID 35379787, 2022). "This is likely caused by the influence of TET2 deficiency on the IL-1β/NLRP3 inflammatory pathway, as treatment with an NLRP3 inflammation inhibitor protected against the development of heart failure." (PMID 35872888, 2022). "Aortic banding triggered the development of heart failure, cardiac hypertrophy, cardiomyocyte hypertrophy, and cardiac fibrosis, and increased NLRP3, NFκB, ASC, IL-1β, cleaved caspase-1 expression, and inflammatory cell infiltration." (PMID 36320147, 2022). "Substantial evidence suggests that activation of the NLRP3 inflammasome in the ischemic heart can exacerbate the myocardial injury, dysfunction, and heart failure through dysregulation of apoptosis, autophagy, oxidative stress, and cardiac inflammation." (PMID 35645816, 2022). "TAC promoted the development of heart failure, and cardiac fibrosis and increased the NLRP3, gasdermin D, ASC, cleaved caspase-1, p-NFκB, IL-1β, and IL-18 levels in myocardial tissue in mice." (PMID 36320147, 2022). "We constructed a rat model of VA‐HF to determine SOX2‐OT expression as well as the mechanism through which silencing SOX2‐OT improves heart failure by inhibiting NLRP3 expression." (PMID 33270361, 2021). "The activation of NLRP3 inflammasomes in mice had been shown to induce heart failure by promoting myocardial inflammation and systolic dysfunction by producing proinflammatory IL-1." (PMID 34795807, 2021).